OLIG2 (oligodendrocyte transcription factor 2)
Diseases named in the same sentence as OLIG2 in open-access papers (continued):
Sharing a sentence is not in itself a finding about the gene and the disease.
hematoma (2 papers, 2016 to 2021). A hematoma is a collection of blood from a vascular structure into an extravascular space. "The CC-1 and Olig2 double immunostaining images showed the quantity of mature oligodendrocytes (CC-1+ Olig2+) in the peri-hematoma region at 7 days post ICH." (PMID 33588866, 2021). "By 14 days, the density of Olig2+ cells declined in the peri-hematoma region, and, by 28 days, it reached the low level seen in the contralateral striatum." (PMID 26743212, 2016). "After ICH, the density of Olig2+ cells increased from 1 to 7 days in the peri-hematoma region, at which time they were ∼11-fold higher than controls and formed a dense band around the hematoma (inset to right)." (PMID 26743212, 2016). "In principle, the increased density of Olig2+ cells observed in the peri-hematoma region could be due to proliferation, migration, or both." (PMID 26743212, 2016).
Hydrocephalus (2 papers, 2020 to 2022). Hydrocephalus is an active distension of the ventricular system of the brain resulting from inadequate passage of CSF from its point of production within the cerebral ventricles to its point of absorption into the systemic circulation. "Hydrocephalus in Rsph9−/− mice also attenuated the expression of myelin basic protein (MBP), which is a marker of myelinating glia, but it enhanced the expression of oligodendrocyte transcription factor 2 (OLIG2), which is a marker of oligodendrocyte progenitor cells and mature oligodendrocytes." (PMID 32709945, 2020).
hypothyroidism (2 papers, 2017 to 2023). Abnormally low levels of thyroid hormone. "Moreover, transient hypothyroidism during demyelination also increased OLIG2 expression in the corpus callosum." (PMID 28875931, 2017). "For example, we did not detect a downregulation of genes related to oligodendrocyte progenitors (i.e., Ng2, Olig1, Olig2) in PTU exposed animals, even though reduced myelination is well established consequence of hypothyroidism." (PMID 36843608, 2023).
leukodystrophy (2 papers, 2021 to 2024). Leukodystrophies are a group of rare, progressive, metabolic, genetic diseases that affect the brain, spinal cord and often the peripheral nerves. "Compared to controls, Olig2-cre:Ptenfl/fl mice, which exhibits Pten loss in Olig2+ cells, displayed gross enlargement of the corpus callosum which was attributed to excess myelin wrapping ultimately leading to leukodystrophy." (PMID 33859549, 2021). "Together, these results indicate that leukodystrophy-related RNF220 mutations impair its regulation of ubiquitination of Olig1 and Olig2 and their protein stability." (PMID 38324685, 2024).
meningioma (2 papers, 2018 to 2020). A generally slow growing tumor attached to the dura mater. "In this cohort, Olig2 was predominantly observed in the nucleus, at the nuclear envelope, and only occasionally in the cytoplasm, thus implying that meningioma cells may behave like oligodendrocyte progenitors." (PMID 29849507, 2018). "Cells positive for SSEA4 and OLIG2 were more frequent in grade II/III meningiomas and the number of FZD9-positive cells was significantly higher in grade II/III meningiomas, although the overall levels remained relatively low, implying that growth of FZD9-positive cells in meningiomas is restricted." (PMID 29849507, 2018). "Regions that were significantly frequently occurring in grade II/III but never in grade I meningiomas included those that were positive for CD133+SOX2±Vimentin+FZD9+GFAP+BTIII+SSEA4+Olig2+, and Nestin+Ki67+CD133+Vimentin+FZD9+GFAP+BTIII+SSEA4+Olig2+." (PMID 29849507, 2018).
teratoma (2 papers, 2017 to 2019). A non-seminomatous germ cell tumor characterized by the presence of various tissues which correspond to the different germinal layers (endoderm, mesoderm, and ectoderm). "We have not tried NSC differentiation through teratoma formation using cells that do not contain any selection markers such as Olig2-GFP or neo; however, it may be possible to obtain NSCs by culturing the rosette tissue from teratomas in NSC culture medium." (PMID 28147316, 2017).
Viral infection (2 papers, 2015 to 2019). "While viral infection did result in limited toxicity to infected OPCs as suggested by morphology, expression of the identifying markers, Pdgfra and Olig2, was retained." (PMID 31625910, 2019). "Viral infection was restricted to the gray matter whereas Olig2 stained cells were observed in both gray and white matter." (PMID 26733813, 2015).
Alpha-thalassemia (1 paper, 2022). Alpha-thalassemia is an inherited hemoglobinopathy characterized by impaired synthesis of alpha-globin chains leading to a variable clinical picture depending on the number of affected alleles. "In addition to histone H3K27M mutation, immunohistochemical staining showed that the tumor cells were positive for glial fibrillary acidic protein, oligodendrocyte transcription factor 2, alpha-thalassemia/mental retardation syndrome X, S-100 and Vimentin." (PMID 35713454, 2022). "Immunohistochemical staining revealed that the tumor cells were positive for GFAP, oligodendrocyte transcription factor 2, histone H3K27M mutant protein, alpha-thalassemia/mental retardation syndrome X, S-100 and Vimentin, but negative for IDH1 R132H, Syn and NeuN." (PMID 35713454, 2022).
amyloid (1 paper, 2024). "Next, we stained amyloid plaques in 12-month-old Bace1fl/fl;AppNL−G−F/wt and Bace1fl/fl;Olig2-Cre; AppNL−G−F/wt mice." (PMID 39548583, 2024). "We crossed the Bace1fl/fl;Olig2-Cre model with heterozygous AppNL−G−F/wt knock-in AD mice to generate AD mice lacking oligodendrocyte Bace1 (Bace1fl/fl;Olig2-Cre; AppNL−G−F/wt) and examined amyloid plaque number and insoluble Aβ levels and gliosis in these animals." (PMID 39548583, 2024).
astrocytic tumor (1 paper, 2024). A glial tumor of the brain or spinal cord showing astrocytic differentiation. "This aberrant discrepancy was also observed in Olig2-CKO and dCKO tdTOM+ astrocytic tumors, in which about 10% of tumor cells are SOX10+." (PMID 39609428, 2024). "This astrocytic phenotype is unlike the highly diffuse Olig2-CKO astrocytic tumors of this study generated from neonatal radial glia in the SVZ." (PMID 39609428, 2024).
Cachexia (1 paper, 2017). Severe weight loss, wasting of muscle, loss of appetite, and general debility related to a chronic disease. "When considering the possible molecular mechanism from FTO via IRX3 to OLIG2 resulting in greater lifelong motor neuron availability, this may have implications for muscle size-related disorders such as sarcopenia and cachexia." (PMID 28103813, 2017).
cerebral infarction (1 paper, 2024). An ischemic condition of the brain, producing a persistent focal neurological deficit in the area of distribution of the cerebral arteries. "This study investigated the relationship between ATP-binding cassette sub-family B member 1 (ABCB1) and OLIG2 single nucleotide polymorphism (SNP) and neurological injury severity and outcome in cerebral infarction (CI)." (PMID 38221931, 2024).
Cerebral ischemia (1 paper, 2025). Restriction of arterial blood supply to the brain associated with insufficient oxygenation to support the metabolic requirements of the tissue. "The reverse transcription (RT)-qPCR results demonstrated that LIPUS treatment increased the expression levels of pro-differentiation-related genes (Olig2 and Sox10), as well as a significant up-regulation of myelin-related genes such as PLP, MBP, and MOG in mice with cerebral ischemia." (PMID 40290135, 2025).
ciliopathy (1 paper, 2022). A genetic disorder of the cellular cilia or the cilia anchoring structures, the basal bodies, or of ciliary function. "In the Olig2-KO mouse or Rfx3-KO (ciliopathy) mouse diencephalon, it was described as a prethalamic malformation, followed by disorganized extension of TCAs." (PMID 35221935, 2022).
COVID-19 (1 paper, 2025). A disease caused by infection with severe acute respiratory syndrome coronavirus 2. "Despite low expression of ACE2 and other known host factors, olfactory epithelium in COVID-19 patients are reportedly infected with two recent studies using COVID-19 autopsy samples demonstrating that SARS-CoV-2 is detected in OLIG2+ or TUBB(TUJ1)+ oligodendrocytes." (PMID 40674406, 2025).
Creutzfeldt-Jakob disease (1 paper, 2022). "However, mature Olig2+ oligodendrocytes were recently shown to decrease at the advanced stages of disease in a murine model of Creutzfeldt-Jakob disease, implying a role in pathogenesis." (PMID 36352465, 2022).
cyst (1 paper, 2020). A sac-like closed membranous structure that may be empty or contain fluid or amorphous material. "The oligodendroglial‐like cells were positive for Olig‐2, and neurons floated in the cyst were positive for NeuN." (PMID 32058680, 2020).
diabetes (1 paper, 2016). "EVA1C is a Slit receptor involved in Robo-mediated axonal guidance, OLIG2 regulates spinal cord oligodendrocyte and motor neuron development, IFNAR1 is an interferon receptor with no role in the initiation or progression of diabetes and RUNX1 is involved in haematopoiesis." (PMID 27195491, 2016).
germ cell tumor (1 paper, 2009). A benign or malignant, gonadal or extragonadal neoplasm that originates from germ cells. "A panel of lineage specific transcription factors including CRX (pineal), OLIG2 (diffuse gliomas) and OCT4 (germ cell tumors) were utilized to “decode” the lineage of the tumor." (PMID 19936203, 2009).
hemangioma (1 paper, 2025). A benign vascular lesion characterized by the formation of capillary-sized or cavernous vascular channels. "Histopathology was conclusive of OLIG2 and SSTR2 negative hemangioma." (PMID 41522408, 2025).
lumbar disk herniation (1 paper, 2018). "Moreover, to determine which cell types express IL-33 and ST2 in a rat model of noncompressive lumbar disk herniation, double staining was performed using anti-IL-33 or anti-ST2 antibodies and antibodies specific for neurons (NeuN), astrocytes (GFAP), microglia (OX-42), or oligodendrocytes (Olig-2)." (PMID 29329586, 2018).
MELAS (1 paper, 2020). "First, qPCR analyses of key motor NPC markers revealed that mRNA levels of OLIG2 and SOX1 were consistently higher in MELAS versus c-MELAS." (PMID 32170107, 2020).
metastatic melanoma (1 paper, 2021). A melanoma that has spread from its primary site to another anatomic site. "Here, we identified that Olig2 mRNA expression was high in primary and metastatic melanoma tissues compared with normal human melanocyte tissues by microarray analysis." (PMID 33833342, 2021). "Olig2 was expressed significantly higher in the four metastatic melanoma cell lines compared with NHEM." (PMID 33833342, 2021). "We found that expression of Olig2 was elevated in primary and metastatic melanoma tissues compared with normal melanocyte tissues." (PMID 33833342, 2021). "In addition, we verified that metastatic melanoma has higher Olig2 protein level than normal human melanocytes and normal skin." (PMID 33833342, 2021). "To examine the basal expression of Olig2, we performed immunoblotting in normal human epidermal melanocytes (NHEM) and four human metastatic melanoma cell lines (MNT-1, 501mel, A375, and HM3KO)." (PMID 33833342, 2021).
neoplasm of the eye (1 paper, 2019). "Gene expression analysis of OLIG2 shows that it is highlyexpressed in neoplasm of the eye, brain, and central nervoussystem." (PMID 31312081, 2019).
neuroepithelial tumors (1 paper, 2024). "The combination of GFAP, Olig-2, synaptophysin, WT-1 and reticulin staining can help differentiate sarcoma and neuroepithelial tumors." (PMID 38926750, 2024).
non-small cell lung carcinoma (1 paper, 2024). A group of at least three distinct histological types of lung cancer, including non-small cell squamous cell carcinoma, adenocarcinoma, and large cell carcinoma. "Additionally, almost all murine GBM CTCs expressed Olig2, and 40% expressed CD133; CSC markers are detected on a fraction of CTCs in a variety of types of cancer, including breast cancer (CD44), colorectal cancer (LGR5), non-small cell lung cancer (NSCLC) and ovarian cancer (BMI1, CD133, ALDH1)." (PMID 38609981, 2024).
oligodendroglial tumor (1 paper, 2005). Oligodendrogliomas are cerebral tumors that are differentiated from other gliomas on the basis of their unique genetic characteristics and better response to chemotherapy. "Id4 expression is present primarily in neoplastic astrocytes in both oligodendroglial tumors and GBM, which is in contrast to the expression patterns of OLIG1 and OLIG2, two survival-associated genes originally identified in GBM tumors." (PMID 16018821, 2005). "An initial report suggested that OLIG1 and OLIG2 might be markers for identification of oligodendroglial tumors." (PMID 16018821, 2005). "In conclusion, we show that Id4 expression is present primarily in neoplastic astrocytes in both oligodendroglial tumors and GBM, which is in contrast to the expression patterns of Olig1 and Olig2, two survival-associated genes originally identified in GBM tumors." (PMID 16018821, 2005).
pineocytoma (1 paper, 2025). "In this case, histopathology confirmed both tumors, with synaptophysin and NSE positivity in the pineocytoma component and GFAP and OLIG2 positivity in the PA component; both showed a low proliferation index (Ki67 < 1%)." (PMID 40585941, 2025).
primitive neuroectodermal tumor (1 paper, 2024). A malignant neoplasm that originates in the neuroectoderm.
proteinopathy (1 paper, 2025). "Subcortical white matter pathways in HIE cases showed salient vulnerability to proteinopathy; Olig2-positive oligodendrocytes were positive for oxidized/misfolded SOD1." (PMID 40277911, 2025).
Pulmonary artery stenosis (1 paper, 2018). An abnormal narrowing or constriction of the pulmonary artery, in the main pulmonary artery and/or in the left or right pulmonary artery branches. "Mek1Y130C mutant mice exhibited pulmonary artery stenosis, cranial dysmorphia and neurological anomalies, including increased numbers of GFAP+ astrocytes and Olig2+ oligodendrocytes in regions of the cerebral cortex." (PMID 29590634, 2018).
sarcoma (1 paper, 2024). A usually aggressive malignant neoplasm of the soft tissue or bone. "The distinct diagnostic features for these tumors included positive GFAP and Olig-2 expression, negativity of WT-1 and reticulin, and a methylation profile incompatible with conventional MC CIC-rearranged sarcomas." (PMID 38926750, 2024).
sleep apnea syndrome (1 paper, 2024). A disorder characterized by multiple cessations of respirations during sleep that induce partial arousals and interfere with the maintenance of sleep. "To address this question, we used an intrauterine hypoxia paradigm that mimics sleep apnea syndrome during pregnancy, as the Olig2+ ASPs start to develop in the DG during the perinatal period." (PMID 39484182, 2024).
spina bifida (1 paper, 2022). A congenital neural tube defect in which vertebrae are not fully formed. "Our data suggest that this process is altered in fetuses with spina bifida due to modifications in Pax6, Olig2, and Nkx2.2 expression throughout the time points studied." (PMID 35782393, 2022). "Based on our data, we propose that NPCs become committed to the astrocyte lineage due the direct exposure to the amniotic fluid in spina bifida by dysregulation in patterning factors, Pax6, Olig2, and Nkx2.2 and potentially downregulating neurogenesis and oligodendrogenesis." (PMID 35782393, 2022). "Therefore, to assess the impact of RA-induced spina bifida on NPC differentiation, we characterized Pax6, Olig2, and Nkx2.2 expression in fetal spinal cords during gestation because in spina bifida the spinal cord is open and unfolded exposing the VZ and the progenitor cells to the amniotic fluid." (PMID 35782393, 2022). "Importantly, we demonstrate a possible implication of Pax6, Nkx2.2, and Olig2 transcription factors, as well as factors in the Notch-BMP signaling pathway, in the premature shift of NPCs into astrocytes in fetuses with RA-induced spina bifida." (PMID 35782393, 2022).
status epilepticus (1 paper, 2014). Status epilepticus is defined as a continuous seizure lasting more than 30 min, or two or more seizures without full recovery of consciousness between any of them. "To test possibility that status epilepticus induces Ttyh1 expression also in oligodendrocytes or microglia, we performed double immunostainings using anti-Ttyh1 antibody and anti-Iba1 (microglia marker) or anti-Olig2 (oligodendrocyte marker) antibody (data not shown)." (PMID 25316497, 2014).
subependymoma (1 paper, 2024). Subependymoma is a rare and slow growing type of ependymoma, often presenting in middle-aged adults, found more commonly in men than in women, usually located in the fourth and lateral ventricles and manifesting with variable symptoms including headache, nausea, and loss of balance. "The majority of cases presented histopathological and immunohistochemical findings (GFAP immunopositivity without expression of Olig2 or SOX10) suggestive of an ependymal differentiation or subependymoma-like features (microcystic changes)." (PMID 38581034, 2024).
teratocarcinoma (1 paper, 2025). A germ cell tumor characterized by the presence of an embryonal carcinoma component and a teratoma component. "The teratoma contained NF-expressing axonal structures, Olig2-positive oligodendrocyte-like cells, GFAP-expressing astrocytic cells and isolated NSE-expressing cells, whereas only GFAP-expressing cells were detected in the teratocarcinoma." (PMID 40217475, 2025).
testis cancer (1 paper, 2024). "Almost all of the top-performing genes were that of over-expression, with PMS2 in THYM; CARD11, LASP1, STIL, POLE, KMT2C, and CLIP1 in testis cancer; ERC1, WRN, OLIG2, FANCC, and ACSL6 in ACC; and SOX2 and NDRG1 in ESCA leading in performance with AUCs ranging 0.832-0.911." (PMID 38491101, 2024).
Thrombocytopenia (1 paper, 2025). A reduction in the number of circulating thrombocytes. "However, short-term, severe, thrombocytopenia led to a significant increase in the percentage of OLIG2+ cells, both in the control SEZ and at 7 dpl, compared to the WT and the Nbeal2-KO mice (magenta bar)." (PMID 41286446, 2025). "Secondly, that transient, severe, thrombocytopenia resulted in increased numbers of OLIG2+ cells; hence, resembling and not contrasting the effects observed in the OPC:platelet co-culture assays." (PMID 41286446, 2025).
ZIKV infection (1 paper, 2022). "We evaluated the effects of ZIKV infection on the oligodendrocyte cell population in the cerebellum using Olig-2 immunostaining as a marker for oligodendrocyte precursor cell population which matures to become oligodendrocytes." (PMID 35969617, 2022).
α-synucleinopathy (1 paper, 2021). "There was no visible colocalization of α-synuclein p-S129 and GFAP as well as Olig2, suggesting that α-synucleinopathy does not jeopardize astrocytes and oligodendrocytes in this mouse line." (PMID 34744697, 2021).